COL10A1 (collagen type X alpha 1 chain)
Diseases named in the same sentence as COL10A1 in open-access papers (continued):
Sharing a sentence is not in itself a finding about the gene and the disease.
cancer (continued). "The TIMER database was utilized to investigate the association between COL8A1, COL10A1, CTHRC1, and FAP, and immune cell infiltration, as immune cell levels correlate with the proliferation and progression of cancer cells." (PMID 35910202, 2022). "Meanwhile, Interrogation of the TCGA Pan-Cancer dataset revealed that COL10A1 is overexpressed across multiple types of human tumors despite different tissue origins." (PMID 33324550, 2020). "COL10A1 is a gene found to be down-regulated in expression in most normal tissues and increased in expression in multiple cancer types." (PMID 32054041, 2020). "Here, we performed an integrative multi-omics analysis across seven digestive cancer types and identified a conserved four-gene signature-DCN, COL10A1, CTHRC1, and TREM2-that is consistently enriched in matrix cancer-associated fibroblasts (mCAFs) and myeloid cells." (PMID 41977392, 2026). "Pan-cancer analysis suggests that COL10A1+Fib may have similar functional roles across multiple major solid tumors." (PMID 40826474, 2025). "Moreover, studies in CRC confirm that COL10A1 is more abundantly expressed in CAFs than in cancer cells." (PMID 40826474, 2025). "Its expression is restricted to matrix-producing cancer-associated fibroblasts (CAFs), rather than cancer cells, and these COL10A1-positive CAFs display immunosuppressive and pro-metastatic properties." (PMID 41303526, 2025). "COL10A1 is one of the collagens and is highly expressed in various types of cancers." (PMID 38345033, 2024). "COL10A1 expression was low in the C4 form in the majority of the 16 cancers." (PMID 38147021, 2023). "Furthermore, increased expression of COL10A1 was usually correlated with late stage of cancers, which was consistent with the results of survival analysis." (PMID 38147021, 2023). "Through this study’s simple analysis, We can tentatively speculate that the overexpression of COL10A1/FAP/FN1 is positively correlated with cancer immunity." (PMID 38063927, 2023). "The findings showed that there were marked differences in the expression of COL10A1 in different immunological and molecular subtypes of several cancers, which can be used as a marker to distinguish the immune and molecular subtypes of tumors, thus guiding clinicians for precise treatment." (PMID 38147021, 2023). "Interestingly, twenty-eight out of 34 cancer types showed significant differences in COL10A1 expression when data from the TCGA and GTEx databases were compared." (PMID 38147021, 2023). "The findings also suggested that COL10A1 may be a significant biomarker for the treatment and prognosis of several cancers." (PMID 38147021, 2023). "Further refinement of this matrix risk signature to specifically predict which lesions will progress to cancer identified a minimum 6-gene risk signature of RSPO1, CTHRC1, SPP1, MMRN1, COL10A1, and PRG4 as the most significant matrisomal predictors of premalignant progression with a ROC AUC of 0.99." (PMID 36404344, 2022). "The expression of COL10A1 in pan-cancer and adjacent normal tissues was first investigated." (PMID 36105715, 2022). "Additionally, the STRING database shows that COL10A1 closely interacts with several proteins, of which some are famously described as potent promoters of cancer stem cells and mesenchymal transformation, such as MMP13, SOX9, and RUNX2." (PMID 36267978, 2022). "The results of this study suggest that COL10A1 may influence the prognosis of cancer patients through its interaction with infiltrating immune cells." (PMID 36105715, 2022). "The ectopic expression of COL10A1 and COL5A2 may affect the development of cancer, leading to genetic mutations and epigenetic alterations." (PMID 33602210, 2021). "COL10A1-positive cells could be observed at a high level in the cancer tissues and metastatic lymph nodes." (PMID 30154451, 2018).
cancer (continued). "The highest expression of genes encoding Col1a1-2, Col3a1, Col4a1, Col4a2, Col5a1, Col5a2, Col6a1, Col8a1, Col9a3, Col10a1, Col12a1, Col14a1, Col15a1, Col16a1, Col18a1, and Col28a1 were detected in untreated tumors, whose landscapes were dominated by Krt8+ cancer cells." (PMID 39372930, 2024). "Consequently, COL10A1 is of great value as a biomarker for immunotherapy of carcinoma." (PMID 38147021, 2023). "Therefore, this study not only elucidates the precise mechanism of COL10A1 in the progression of GC but also provides molecular insight into cancer-related ECM and may serve as a predictor of clinical outcome in GC." (PMID 30154451, 2018). "This component features COL10A1, ITIH5, ADIPOQ, ADAMTS5, GPC3, SFRP1, and RARRES2 genes, pointing to their involvement in cancer-related cellular structures." (PMID 38253993, 2024). "Then, we examined the correlation between COL10A1 expression levels and infiltration of immune cells, immune and stromal cell scores, TMB, MSI, and immunotherapy cohorts in pan-cancers." (PMID 38147021, 2023). "Therefore, abnormally high level of COL10A1 may predict the development of malignant tumors." (PMID 38147021, 2023). "This study also investigated the signaling pathways involved in COL10A1/FAP/FN1, and the results showed that FN1 is a component of the extracellular matrix (ECM), which is a characteristic gene for cancer." (PMID 38063927, 2023). "This activation of CAF-specific gene signatures was corroborated by co-modularization of key CAF type markers with COL10A1 across the breast and pancreatic ColX modules, which highlight CAF heterogeneity as well as common features of CAF-mediated aggression in both cancer types." (PMID 39939916, 2025). "Furthermore, our team found that COL10A1 was strongly correlated with two immunotherapy biomarkers, TMB and MSI, in a variety of cancers." (PMID 38147021, 2023). "In this study, COL10A1 was identified as being correlated with TMB and MSI in cancers." (PMID 38147021, 2023). "Firstly, by examining the expression levels of the COL10A1/FAP/FN1, we can sensitively detect whether COVID-19 infection is promoting cancer progression." (PMID 38063927, 2023). "COL10A1 and COL5A2 are members of the collagen family, and the dysregulation of COL10A1 and COL5A2 may represent a basis for cancer invasion and migration." (PMID 33602210, 2021). "The overexpressed integrin α (ITGA) subfamily genes ITGA2 and ITGA3 are predicted to be involved in cancer-related pathways such as PI3K-Akt signaling pathway and FA interacting with ECM genes such as laminin (LAMB3, LAMA3, and LAMC2) and collagen (COL10A1, COL12A1)." (PMID 34262595, 2021). "Furthermore, the focal adhesion genes such as COL1A1, COL10A1, and COL11A1 were also found to be up-regulated in the present study and are also reported to be up-regulated in various cancers including breast tumours." (PMID 31292488, 2019). "The second report detected expression of COL10A1 mRNA by microarray analysis in diverse cancer types but not in normal tissues." (PMID 29212713, 2017). "Interestingly, most of these genes (25 genes) were down-regulated, and only 3 genes (COL10A1, MMP11, and TUBB3) were up-regulated in cancer tissues." (PMID 26084486, 2015). "Other predicted blood-secretory marker proteins such as PAICS, CHRDL1, KLF2, COL10A1 and MYL9 have not heretofore been reported to be cancer related." (PMID 21060876, 2010). "COL10A1 is not expressed in normal colon epithelium, but is a direct transcriptional target of RUNX2, a transcription factor that is expressed in cancer cells, and has been related to multiple cancers." (PMID 25215506, 2014).
skeletal diseases (4 papers, 2011 to 2021). "From these candidate TFs, we identified many potential Col10a1 transactivators and repressors that promote or inhibit chondrocyte hypertrophy and are associated with skeletal diseases." (PMID 34276786, 2021). "Further characterization of these candidate Col10a1 transcriptional regulators could help identify novel therapeutic targets for skeletal diseases associated with abnormal chondrocyte hypertrophy." (PMID 34276786, 2021). "Meanwhile, as a specific marker of hypertrophic chondrocytes, the type X collagen gene (COL10A1) is also critical for endochondral bone formation, as mutation and altered COL10A1 expression are often accompanied by abnormal chondrocyte hypertrophy in many skeletal diseases." (PMID 25321476, 2014). "Further characterization of this Runx2-Col10a1 interaction has the potential to identify novel therapeutic targets for multiple skeletal diseases showing altered Col10a1 expression and chondrocyte maturation." (PMID 21887706, 2011). "Further characterization of these candidate Col10a1 regulators will open new avenues of research that aims to better understand skeletal developmental and disease and thus better options developing new therapeutic targets for skeletal diseases." (PMID 34276786, 2021). "Therefore, understanding the molecular regulation of cell-specific Col10a1 expression is essential to understanding the basic mechanisms of bone growth as well as the pathogenesis of Col10a1-related skeletal diseases." (PMID 21887706, 2011). "Further characterization of these candidate Col10a1 regulators will open up new avenues of research that aims to better understanding skeletal developmental and disease mechanisms and may hold promise for pharmaceutical purpose to develop therapeutic targets for relevant skeletal diseases." (PMID 25321476, 2014).
skeletal dysplasia (4 papers, 2011 to 2021). Any Mendelian diseases that affects growth and development of the skeleton. "Conversely, inhibitors or insufficient transactivators may decrease Col10a1 expression and delay chondrocyte maturation and thus contribute to low bone growth as seen in skeletal dysplasia, or less cartilage degradation as seen in Runx2+/− mice of an OA mouse model." (PMID 34276786, 2021). "In MCDS mice expressing the Col10a1.pN617K mutation, CBZ reduced the MCDS-associated expansion of the growth plate hypertrophic zone, attenuated enhanced expression of ER stress markers such as Bip and Atf4, increased bone growth, and reduced skeletal dysplasia." (PMID 28920921, 2017).
connective tissue disorder (2 papers, 2013 to 2020). A disease involving the connective tissue. "Other networks significantly enriched also related to a further network in connective tissue disorders that contained genes including collagens COL10A1, COL11A1 and COL2A1 plus a disintegrin and metalloproteinase with thrombospondin motifs-2 (ADAMTS-2) and fibulin-1 (FBLN1)." (PMID 23971731, 2013).
adenocarcinoma (1 paper, 2022). A common cancer characterized by the presence of malignant glandular cells. "We identified significant overlap in the SqCC and adenocarcinoma risk signatures for matrix components that regulate collagen fibril architecture including COL10A1, COL11A1, and CTHRC1 suggesting that our risk signature represents changes in the organization of fibrillar collagens." (PMID 36404344, 2022).
autosomal dominant inherited disorder (1 paper, 2019). "There is no doubt that MCDS is an autosomal dominant inherited disorder, resulting from heterozygous mutation of the COL10A1 gene." (PMID 31856751, 2019).
genetic disorders (1 paper, 2015). "The immobilization-only genes included collagen genes Col2a1, Col10a1, and Col11a1, all previously associated with human genetic disorders with altered joint mobility." (PMID 26006773, 2015).
COL10A1 also shares sentences with these, for which no sentence is quoted: esophageal cancer (4 papers); atherosclerosis (2); cartilage disease (2); colon adenocarcinoma (2); infection (2); ovarian carcinoma (2); ameloblastoma (1); benign breast disease (1); brain cancer (1); cholangiocarcinoma (1); chronic pancreatitis (1); co-infection (1); depression (1); diabetes (1); ductal breast carcinoma in (1); fallopian tube tumors (1); Fuchs' endothelial dystrophy (1); gastrointestinal tumors (1); head and neck squamous cell carcinoma (1); hepatocellular carcinoma (1); intraductal cribriform breast adenocarcinoma (1); invasive ductal breast carcinoma (1); invasive lobular breast carcinoma (1); keratoconus (1); leukaemia (1); liver fibrosis (1); male breast carcinoma (1); melanoma (1); muscle disorders (1); Myocardial fibrosis (1).
A further 13 diseases each share a sentence with COL10A1 in 1 paper.